SLC10A1 (solute carrier family 10 member 1)
Description:
As a major transporter of conjugated bile salts from plasma into the hepatocyte, it plays a key role in the enterohepatic circulation of bile salts necessary for the solubilization and absorption of dietary fat and fat-soluble vitamins. It is strictly dependent on the extracellular presence of sodium. It exhibits broad substrate specificity and transports various bile acids, such as taurocholate, cholate, as well as non-bile acid organic compounds, such as estrone sulfate. Works collaboratively with the ileal transporter (NTCP2), the organic solute transporter (OST), and the bile salt export pump (BSEP), to ensure efficacious biological recycling of bile acids during enterohepatic circulation. (Microbial infection) Acts as an entry receptor for hepatitis B virus (HBV). The recognition for human SLC10A1/NTCP is highly specific.
Synonyms: NTCP; NTCP1; FHCA2
Tractability: Small molecule: a structure with a bound ligand is known; a high-quality ligand is known; it belongs to a druggable protein family. Antibody: UniProt places it where antibodies can reach, with high confidence; its Gene Ontology location is reachable by antibodies, with high confidence; UniProt predicts a signal peptide or a membrane-spanning region. PROTAC: its protein half-life has been measured; a small molecule that binds it is known. Other modalities: an approved drug acts on it.
Target class: SLC superfamily of solute carriers; Electrochemical transporter; SLC10 family of sodium-bile acid co-transporters; Transporter
Gene: Protein-coding gene on chromosome 14 (69,775,358 to 69,797,285, reverse strand). Ensembl gene ENSG00000100652.
Subcellular location: Cell membrane
Pathways (Reactome):
Metabolism: Recycling of bile acids and salts
Gene Ontology:
Molecular function: bile acid transmembrane transporter activity; protein binding; bile acid:sodium symporter activity
Biological process: bile acid and bile salt transport; cellular response to xenobiotic stimulus; response to estrogen; response to ethanol; response to nutrient levels
Cellular component: plasma membrane; basolateral plasma membrane; membrane
Genetic constraint (gnomAD): Loss-of-function variants: 34 observed, 19.93 expected, observed/expected ratio (o/e) 1.71, 90% interval 1.27 to 1.96. The upper end of that interval is the gene's LOEUF score, 1.96, which puts it in group 6 of 6, group 1 being the genes least tolerant of losing a copy. Missense variants: 541 observed, 457.95 expected, observed/expected ratio (o/e) 1.18, 90% interval 1.1 to 1.27. Synonymous variants: 186 observed, 172.46 expected, observed/expected ratio (o/e) 1.08, 90% interval 0.96 to 1.22.
Homologues: Orthologues: chimpanzee SLC10A1 (99% identical), macaque SLC10A1 (96% identical), dog SLC10A1 (86% identical), pig SLC10A1 (81% identical), rat Slc10a1 (77% identical), mouse Slc10a1 (77% identical), guinea pig SLC10A1 (66% identical), zebrafish slc10a1 (46% identical), tropical clawed frog slc10a1 (44% identical). Paralogues in human: SLC10A6 (35% identical), SLC10A4 (34% identical), SLC10A2 (33% identical), SLC10A3 (26% identical), SLC10A5 (23% identical).
Diseases named in the same sentence as SLC10A1 in open-access papers:
SLC10A1 is named in the same sentence as 67 diseases in open-access papers, as found by Europe PMC text mining. Sharing a sentence is not in itself a finding about the gene and the disease. The quoted sentences say what the papers report.
hepatoma (53 papers, 2012 to 2025). "SLC10A1 encodes NTCP, and the mutation S267F can decrease the risk of cirrhosis and hepatocellular carcinoma and confer a protective effect against chronic hepatitis B. People carrying S267F exhibit significantly elevated bile acidemia during childhood." (PMID 38890579, 2024). "Unlike hepatoma cell lines, iPSC-derived liver organoids endogenously expressed high levels of the HBV entry factor sodium-taurocholate cotransporting polypeptide (NTCP, encoded by SLC10A1)." (PMID 33241206, 2021).
cholestasis (46 papers, 2012 to 2026). Impairment of the bile flow caused by obstruction within the liver, or outside the liver in the bile duct system. "Hepatic transporters are implicated in the mechanisms of cholestasis, including sodium-taurocholate cotransporting polypeptide (NTCP, SLC10A1/Slc10a1) and Organic anion transporting polypeptide (OATP), multidrug resistance associated protein (MRP2) and canalicular bile salt export pump (BSEP)." (PMID 38362143, 2024). "In agreement with previous data which we had described for the hepatic uptake transporters SLC22A1/OCT1 and SLCO1B1/OATP1B1 cholestasis, alcohol consumption, and inflammation determined by C-reactive protein altered SLC10A1/NTCP expression whereas age and gender are of minor importance." (PMID 35806468, 2022). "In this regard, the downregulation of CYP7A1, organic anion transporter 1B1 and SLC10A1 in two donors is compliant with the AOP on drug-induced cholestasis and confirms results previously obtained in spheroid cultures of HepaRG cells and in PHH in long-term 2D-sandwich culture." (PMID 34681664, 2021). "Consistently, nine genes in the fatty acid metabolism, phospholipidosis and steatosis pathways including Acot2, Ugt2a1, Cd36 and Retn were upregulated in the cirrhotic liver post SPION injection accompanied with elevated Tgfb1 and sodium bile acid cotransporter (Slc10a1) of the cholestasis pathway." (PMID 27357559, 2016). "In chlorpromazine-derived cholestasis, increased MRP4 expression has been observed, along with a decreased expression of NTCP (SLC10A1), to avoid the influx of more BAs." (PMID 40064699, 2025). "In general, expression of Slc10a1 was low compared with that in healthy controls, most likely an FXR-induced hepatoprotective effect as a result of cholestasis." (PMID 38074508, 2024). "In children with early- and late-stage cholestasis, SLC10A1 and CYP7A1 were significantly downregulated, suggesting that these two genes contribute to cholestasis in human." (PMID 29177108, 2012). "The SLC10A1 mRNA expression showed a 44-fold variation (coefficient of variation: 66%) and was significantly affected by age, inflammation (i.e., C-reactive protein [CRP] levels), cholestasis, smoking, and alcohol consumption." (PMID 35806468, 2022).
viral infection (18 papers, 2012 to 2026). "This analysis reveals the overlapping pattern of the dual function of NTCP and suggests the possible impact of SLC10A1 SNPs on virus infection." (PMID 41544142, 2026).
liver diseases (8 papers, 2018 to 2026). "The diverse NTCP compatibility to preS1 by SLC10A1 SNPs may affect HBV/HDV infection susceptibility and pathogenesis of the related liver diseases, as the case with rs2296651 (causing S267F substitution), which is a future subject to be analyzed." (PMID 41544142, 2026).
Hyperbilirubinemia (6 papers, 2017 to 2025). An increased amount of bilirubin in the blood.
chronic hepatitis B (5 papers, 2021 to 2026). "NTCP, encoded by the SLC10A1 gene, is a cellular receptor for HBV and is significantly associated with resistance to chronic hepatitis B." (PMID 38890579, 2024). "Moreover, SLC10A1 serves as a receptor for the hepatitis B virus (HBV), and this variant can increase resistance to chronic hepatitis B." (PMID 38890579, 2024).
liver cancer (5 papers, 2017 to 2024). An epithelial or non-epithelial malignant neoplasm that arises from the liver. "The results showed that UBE2C, PTTG1, TOP2A and SPP1 were positive, FCN3, SLC22A1, ADH4, CYP2C8, SLC10A1, and FBP1 were negative in liver cancer tissues." (PMID 38664521, 2024).
NTCP deficiency (4 papers, 2017 to 2024). "According to previous reports, seven different mutations of the SLC10A1 gene have been linked to NTCP deficiency." (PMID 35937832, 2022). "Then, several cases with deleterious SLC10A1 mutations causing NTCP deficiency have been published and all NTCP-deficienct patients presented hypercholanemia characterized by elevated BA levels in the circulation." (PMID 35937832, 2022). "When aged 25 days, the infant underwent SLC10A1 analysis to evaluate the possibility of NTCP deficiency." (PMID 29290974, 2017). "In this study, two unrelated infants were diagnosed to have NTCP deficiency by way of Sanger sequencing of the SLC10A1 gene." (PMID 29290974, 2017). "In summary, by way of clinical and SLC10A1 genetic analysis, we diagnosed two unrelated infants with NTCP deficiency, who presented with indirect hyperbilirubinemia and marked hypercholanemia as early as in the neonatal period." (PMID 29290974, 2017). "The p.Ser267Phe mutation in the SLC10A1 gene can cause NTCP deficiency." (PMID 35937832, 2022).
breast carcinoma (3 papers, 2017 to 2023). "Twenty of the 27 common genes have published data presenting that these genes were associated with breast cancer, but seven genes (DUSP10, GABRA6, GABRR1, KIF21B, KLHL24, MAP2K2, and SLC10A1) might be passenger genes or have not yet been studied regarding their pathological roles in breast cancer." (PMID 28973975, 2017).
gallstones (3 papers, 2015 to 2022). Solid crystalline precipitates in the biliary tract, usually formed in the gallbladder, resulting in the condition of cholelithiasis. "The etiology of gallstones may include NTCP deficiency, which is encoded by the SLC10A1 gene." (PMID 36362164, 2022).
hepatoblastoma (2 papers, 2022 to 2024). Hepatoblastoma (HB) is a malignant hepatic tumor and is the most common pediatric liver cancer. "Furthermore, another investigation has revealed that the expression of NTCP (SLC10A1) is downregulated in hepatoblastoma cells and tissues." (PMID 38390281, 2024).
vitamin D deficiency (2 papers, 2017 to 2022). A nutritional condition produced by a deficiency of VITAMIN D in the diet, insufficient production of vitamin D in the skin, inadequate absorption of vitamin D from the diet, or abnormal conversion of vitamin D to its bioactive metabolites. "Individuals with homozygous p.Ser267Phe in SLC10A1 are prone to vitamin D deficiency, deviated sex hormones and blood lipids." (PMID 28835676, 2017).
cholelithiasis (1 paper, 2022). The presence of crystallized deposits forming in the gallbladder or biliary tree, primarily composed of cholesterol, bilirubin, and bile. "Interestingly, NTCP knockout (SLC10A1−/−) mice develop multiple abnormal phenotypes of the gallbladder and hypercholanemia, but not cholelithiasis." (PMID 36362164, 2022).
infection (101 papers, 2012 to 2026). The state of being infected such as from the introduction of a foreign agent such as serum, vaccine, antigenic substance or organism. "In the binding of HBV to the cell surface, NTCP (encoded by the SLC10A1 gene) is convinced to play a crucial role as a receptor for HBV in the establishment of its infection." (PMID 36560460, 2022). "Hepatitis B virus initiates infection of host cells by binding of the virally encoded preS1 to the host membrane protein NTCP, which is encoded by the gene SLC10A1." (PMID 31798562, 2019).
tumor (17 papers, 2014 to 2025). "The impact of genetic variants on SLC10A1 gene expression was additionally independently evaluated in adjacent non-tumor tissues (n = 50) of the liver hepatocellular carcinoma (LIHC) cohort of The Cancer Genome Atlas (TCGA)." (PMID 35806468, 2022). "It has been reported that overexpression of SLC10A1 at the cellular level exhibits a significant tumour suppressive effect, inhibiting aerobic glycolysis and HCC proliferation and migration." (PMID 38418897, 2024). "Previous research reported that SLC10A1 (solute carrier family 10 member 1) can inhibit the Warburg effect to suppress HCC tumor growth." (PMID 36246607, 2022). "The expression levels of AR, CAT, CYP3A4, ESR1 and SLC10A1 were markedly upregulated in primary tumour tissues compared with normal tissues." (PMID 34717619, 2021). "Down-regulated SLC10A1 is correlated with poor post-surgery survival rate and larger tumor tissue mass in HCC patients and ectopic expression of NTCP significantly suppresses HCC cell proliferation." (PMID 32576292, 2020). "Another gene that was considerably down-regulated within the tumor was sodium dependent taurocolic cotransporting polypeptide (NTCP/ SLC10A1), which was recently identified as a receptor for human hepatitis B virus." (PMID 25141867, 2014). "This could be confirmed using SLC10A1 gene expression and germline genetic data from adjacent non-tumor liver tissue from the hepatocellular cohort of TCGA." (PMID 35806468, 2022). "In this study, we for the first time showed that LECT2, SLC10A1, CYP3A4, and HSD17B13 can suppress HCC tumor growth by inhibiting Warburg effect." (PMID 32576292, 2020).
cancer (3 papers, 2020 to 2025). A tumor composed of atypical neoplastic, often pleomorphic cells that invade other tissues. "Overexpression of SLC10A1, which inhibits the production of Ado and decreases HIF‐1α mRNA and protein expression in cancer cells, is consistent with the reduced expression of HIF‐1α in AR 292 and AR 357‐treated PCa cell lines." (PMID 40181576, 2025).
bladder (2 papers, 2015 to 2024). "However, FCN3, SLC22A1, ADH4, CYP2C8, SLC10A1, F9, and FBP1 were significantly downregulated in HCC tissue compared to the matched para-carcinoma tissue." (PMID 38664521, 2024).
infectious disease (1 paper, 2017). A disorder directly resulting from the presence and activity of a microbial, viral, or parasitic agent in humans. "Characterizing patterns of nucleotide diversity at candidate loci (e.g., SLC10A1) with susceptibility to persistent HBV infection, and testing for signatures of natural selection may be informative for identifying functional loci that are related to susceptibility to this infectious disease." (PMID 28429786, 2017).
metabolic disease (1 paper, 2024). A congenital disorder (due to inherited enzyme abnormality) or acquired (due to failure of a metabolically important organ) disorder resulting from an abnormal metabolic process. "NTCP (SLC10A1) and ASBT (SLC10A2), as bile acid transporters, are indeed associated with the occurrence and development of metabolic diseases and may be potential therapeutic targets." (PMID 39850557, 2024).
SLC10A1 also shares sentences with these, for which no sentence is quoted: hepatitis B virus infection (12 papers); Cirrhosis (10); Obesity (6); Hepatitis (5); Hepatic steatosis (4); liver fibrosis (4); hepatitis D (3); intrahepatic cholestasis (3); viral hepatitis (3); Alagille syndrome (2); cholangiocarcinoma (2); cholestatic jaundice (2); Cholestatic liver disease (2); familial intrahepatic cholestasis (2); liver dysfunction (2); non-alcoholic steatohepatitis (2); Pruritus (2); Sepsis (2); steatosis (2); Aagenaes syndrome (1); adenocarcinoma (1); adenoma (1); Allergy (1); atherosclerosis (1); cholangitis (1); coinfection (1); colon tumor (1); developmental delay (1); diabetes (1); Dubin-Johnson syndrome (1).
A further 18 diseases each share a sentence with SLC10A1 in 1 paper.